MSMP (microseminoprotein, prostate associated)
Description:
Acts as a ligand for C-C chemokine receptor CCR2. Signals through binding and activation of CCR2 and induces a strong chemotactic response and mobilization of intracellular calcium ions. Exhibits a chemotactic activity for monocytes and lymphocytes but not neutrophils.
Synonyms: PSMP; PC-3
Tractability: Antibody: UniProt places it where antibodies can reach, with high confidence; UniProt predicts a signal peptide or a membrane-spanning region; its Gene Ontology location is reachable by antibodies, with medium confidence. PROTAC: ubiquitination databases record sites on it.
Gene: Protein-coding gene on chromosome 9 (35,752,990 to 35,756,613, reverse strand). Ensembl gene ENSG00000215183.
Subcellular location: Secreted
Subcellular location (Human Protein Atlas): Vesicles; Cytosol; Predicted to be secreted
Gene Ontology:
Molecular function: CCR2 chemokine receptor binding
Biological process: lymphocyte chemotaxis; monocyte chemotaxis
Cellular component: cytoplasm; extracellular region
Genetic constraint (gnomAD): Loss-of-function variants: 9 observed, 16.36 expected, observed/expected ratio (o/e) 0.55, 90% interval 0.33 to 0.96. The upper end of that interval is the gene's LOEUF score, 0.96, which puts it in group 4 of 6, group 1 being the genes least tolerant of losing a copy. Missense variants: 170 observed, 183.09 expected, observed/expected ratio (o/e) 0.93, 90% interval 0.82 to 1.05. Synonymous variants: 64 observed, 68.28 expected, observed/expected ratio (o/e) 0.94, 90% interval 0.76 to 1.15.
Homologues: Orthologues: chimpanzee MSMP (99% identical), macaque MSMP (99% identical), dog MSMP (94% identical), pig MSMP (93% identical), mouse Msmp (91% identical), rabbit MSMP (91% identical), rat Msmp (91% identical), guinea pig MSMP (89% identical), tropical clawed frog msmp (46% identical), zebrafish msmp1 (37% identical), zebrafish msmp2 (26% identical). Paralogues in human: MSMB (16% identical).
Diseases named in the same sentence as MSMP in open-access papers:
MSMP is named in the same sentence as 19 diseases in open-access papers, as found by Europe PMC text mining. Sharing a sentence is not in itself a finding about the gene and the disease. The quoted sentences say what the papers report.
prostate carcinoma (4 papers, 2019 to 2024). A carcinoma that arises from epithelial cells of the prostate gland. "MSMP is up-regulated in prostate cancer cells in hypoxic conditions, resulting in increased drug resistance." (PMID 38396744, 2024).
dementia (1 paper, 2025). Loss of intellectual abilities interfering with an individual's social and occupational functions. "Top proteins with high feature importance in the clinical impairment signature again highlighted ACHE and NPTXR as well as additional targets linked to neuroplasticity (EPHA4 and CNTFR) and immune activation (MSMP and KLK3), underscoring their potential for transdiagnostic dementia staging." (PMID 40665048, 2025).
ovarian carcinoma (1 paper, 2022). A malignant neoplasm originating from the surface ovarian epithelium. "Given that MSMP has been identified as a novel CCR2 ligand and cancer-secreted protein, we then tested MSMP expression in ovarian cancer cells by qRT-PCR." (PMID 35094142, 2022). "Collectively, the bioinformatics analysis of TCGA data indicated that expression of CCR2 and its ligand MSMP was related with macrophage infiltration in ovarian cancer." (PMID 35094142, 2022). "We found that MSMP expression was relatively high in ovarian cancer." (PMID 35094142, 2022). "Notably, our previous study showed that the interaction of microseminoprotein (MSMP), a CCR2 ligand, with CCR2 plays an important role in promoting adaptive resistance to AVA in ovarian cancer models." (PMID 35094142, 2022). "In this study, we sought to investigate the role of MSMP/CCR2 signaling in macrophage polarization and the effects of targeting CCR2+ macrophages with bromodomain and extra-terminal domain (BET) inhibitors (BETi) in ovarian cancer, especially in the context of enhancing the efficacy of AVA therapy." (PMID 35094142, 2022).
cancer (5 papers, 2019 to 2022). A tumor composed of atypical neoplastic, often pleomorphic cells that invade other tissues. "Controlling the false discovery rate at 5%, ECAR selected six genes CHRM3, CTCFL, KCNE2, MLANA, MSMP, TTLL2, many of which have been reported to be associated with lung function or cancer." (PMID 34857823, 2021). "A literature search showed that many of these altered genes, such as IGF2, FAM83A, CEACAM5 and CEACAM6, STC1 and MSMP, play a role in PCa or other types of cancer." (PMID 31500347, 2019).
tumor (3 papers, 2019 to 2024). "Given the potential role of MSMP/CCR2 in TAM recruitment in the tumor microenvironment, we analyzed CCR2 expression across immune cells with use of the DICE database." (PMID 35094142, 2022).
MSMP also shares sentences with these, for which no sentence is quoted: colitis (3 papers); Hepatic fibrosis (2); acute kidney injury (1); adenocarcinoma (1); benign prostate hyperplasia (1); colonic tumor (1); COVID-19 (1); Crohn disease (1); kidney cancer (1); liver disease (1); lung carcinoma (1); prostate (1); Stroke (1); ulcerative colitis (1).